ELN (elastin)
Diseases named in the same sentence as ELN in open-access papers (continued):
Sharing a sentence is not in itself a finding about the gene and the disease.
diabetes (46 papers, 2012 to 2025). "Lastly, this method is not suitable for patients with risk factors for wound healing complications, including diabetes, ischemic disease, active infection, and conditions associated with collagen or elastin abnormalities (e.g., Ehlers-Danlos syndrome)." (PMID 40135006, 2025). "Cardiac remodeling in type 2 diabetes mellitus is also linked to elastin degradation and autoimmunity to elastin, anti-elastin antibodies were significantly elevated in type 2 diabetes patients and linked with progression of left ventricular hypertrophy." (PMID 37001705, 2023). "The elastic properties of the arterial wall as defined by two major proteins (elastin and collagen) are altered with aging and accelerated in the presence of risk factors such as diabetes over a lifespan, resulting in increased arterial stiffness." (PMID 37304050, 2023). "Chronically high levels of glucose, as seen in patients with diabetes mellitus, causes a higher degree of cross-linking in collagen and elastin via the formation of advanced glycation end-products and premature cellular senescence in dermal fibroblasts." (PMID 25874752, 2015). "Untreated diabetes was also associated with reduced ratio of elastin to collagen that was prevented by vitamin D supplementation." (PMID 22631050, 2012). "Particularly in diabetes, aortic stiffness may be accelerated by long-term hyperglycemia and formation of AGEs on the arterial wall, with loss of elastin and increased collagen cross-links." (PMID 35568947, 2022). "In summary, we have shown that the ARB telmisartan prevents aortic stiffening associated with untreated STZ-diabetes in the context of improved structural properties of the aortic wall such as preservation of the concentration and organisation of elastin network." (PMID 24920962, 2014). "As diabetes mellitus (DM) is a major risk factor for atherosclerosis, advanced glycation end products (AGEs) increase arterial wall stiffness by cross-linking with elastin and collagen, or accelerate foam cell formation by cross-linking with oxLDL." (PMID 36411459, 2022). "Previous findings showed that streptozotocin-induced diabetes caused alterations in the ultrastructure of the granular pneumocytes in the inter-alveolar septae, the non-ciliated bronchiolar epithelial (Clara) cells and the collagen and elastin in the alveolar walls." (PMID 26185997, 2015). "The central arteries become stiffer with aging and diabetes by losing elastin and accumulating collagen, while the peripheral arteries that contain more smooth muscle cells are not similarly affected by aging." (PMID 41374029, 2025). "Cathepsin S is a potent cysteine protease active at neutral pH, enabling it to act extracellularly in degrading collagen and elastin, and has been noted to be elevated in diabetes." (PMID 41373586, 2025). "Diabetes causes ECM remodeling characterized by collagen deposition, elastin reduction, and fragmentation, leading to decreased vascular compliance." (PMID 41440035, 2025). "Arterial stiffness is caused by a combination of variables such as an imbalance in elastin collagen ratio, oxidative stress, chronic inflammation, and so on, and diabetes can accelerate this process." (PMID 36712669, 2022). "Previous studies proposed that chronic inflammation in diabetes has a role in abnormal collagen production and elastin degradation, which promotes arterial stiffness." (PMID 34330221, 2021). "Medial elastin-specific calcification is observed in many different diseases such as Monckeberg’s sclerosis, aging, diabetes, and end-stage renal failure." (PMID 34203711, 2021). "Hyperglycaemia in diabetes will induce abnormal collagen production and elastin reduction that allows the formation of arterial stiffness." (PMID 34330221, 2021). "Medial calcification, also known as Mönckeberg’s arteriosclerosis, is most often found in patients with chronic kidney disease and diabetes mellitus, characterized by mineral deposition along the elastin lamellae." (PMID 34203711, 2021).
diabetes (continued). "Despite the fact that it seems unlikely for the lungs to be affected by diabetes, their great vascularization and richness in collagen and elastin fibers make the pulmonary parenchyma a potential target for the diabetes milieu." (PMID 32344939, 2020). "In diabetic rats, the relative amounts of collagen, elastin, and basal laminae in the septum are increased and diabetes induction by streptozotocin, in 3 week old rats, results in increased collagen and elastin." (PMID 31108840, 2019). "Another study examining normally fed and undernourished diabetic rats concludes that experimental diabetes affects lung connective tissue metabolism and breakdown and thereby leads to increases in lung collagen and elastin." (PMID 31108840, 2019). "With aging and diabetes elastin is replaced by collagen, leading to arterial stiffness and endothelial dysfunction." (PMID 27898103, 2016). "AGEs accumulate on collagen and elastin in the vessel wall and are likely involved in the increase in vascular stiffness seen in diabetes." (PMID 27708615, 2016). "Such loss of elasticity arises from alterations in collagen and elastin structure and function which may arise from the increased oxidative stress, carbonyl stress, and advanced glycation end products associated with the relative hyperglycaemia of diabetes and prediabetes." (PMID 27382575, 2016). "For example, increased cross-linking of the elastin network with diabetes could theoretically impair interlamellar sliding." (PMID 38094616, 2023). "Similarly, streptozotocin-induced diabetes in rats was accompanied by increased bladder elastin content." (PMID 37283037, 2023). "The increased glycation of elastin is an important factor in vascular changes in diabetes." (PMID 35997390, 2022). "Considering its large vascular network and richness in collagen and elastin, the pulmonary system is susceptible to undergoing microvascular damage and nonenzymatic glycation in diabetes." (PMID 26185997, 2015). "ECM components including fibrillar collagens and elastin may accumulate glucose-derived cross-links with both increasing age and diabetes, which may, in turn, affect the molecular and hence macromechanical properties of tissues." (PMID 25014552, 2014). "Significantly lower levels of elastin, collagen and MMP-12 were found in patients with diabetes as compared with non- diabetics." (PMID 25803692, 2015). "ECM alterations in diabetes are characterized by increased collagen and reduced elastin, which are not uniform across different vascular beds and are also sex -dependent." (PMID 41440035, 2025). "Maillard adducts to connective tissue products formed due to non-enzymatic abnormal glycation of collagen and elastin in patients with diabetes offer a possible explanation for the pathogenesis of the disease." (PMID 39323702, 2024). "This might not surprise as the large vascular network and high collagen and elastin composition of the pulmonary system, is prone to microvascular damage and nonenzymatic glycation in diabetes." (PMID 35177082, 2022).
Marfan syndrome (40 papers, 2010 to 2025). A disorder of the connective tissue. "Individuals with Marfan syndrome have a genetic predisposition for elastic fiber fragmentation and elastin degradation and are prone to early aneurysm formation and progression." (PMID 39795873, 2024). "Fibrillin 2 (FBN2) was first discovered while studying Marfan syndrome, and its encoded products are associated with elastin fibres." (PMID 37337404, 2023). "In Marfan syndrome, however, the inability to properly code for the protein fibrillin-1 prematurely leads to the degradation and loss of elastin fiber integrity in the ECM." (PMID 35560311, 2022). "The comparison between BAV and Marfan syndrome is justified due to common histological features affecting elastin fibers, vSMC, and due to an increased risk of aortic dissection in both pathologies." (PMID 31024329, 2019). "In human Marfan syndrome, a hereditary disorder of the fibrillar metabolism, cystic medial necrosis is a typical finding and associated loss of elastin has been mentioned." (PMID 26581331, 2015). "Marfan syndrome is characterized by decreased aortic distensibility, increased stiffness index, and increased pulse wave velocity due to fibrillin-1 deficiency and abnormal elastin synthesis." (PMID 40559232, 2025). "Additionally, underlying connective tissue disorders affecting fibrillin or elastin, such as Marfan syndrome, may predispose individuals to dural weakness." (PMID 39507181, 2024). "Research into Marfan syndrome mainly focuses on the pathophysiology involved in the degeneration of elastin-rich elastic fibers, which are essential components of the aortic wall." (PMID 40497939, 2025). "Our study is relevant to human aorta pathology because the aorta of patients with Marfan Syndrome appears to exhibit similar disruption of fibrillin-1–elastin interactions." (PMID 39120288, 2024). "Since fibrillin-1 defect is related to Marfan Syndrome, a human genetic disorder that severely impacts connective tissues, we detected if the fibrillin-1 interaction with elastin is also altered in the aortas of Marfan patients." (PMID 39120288, 2024). "In Marfan syndrome and LOX mutations, corneal elastin is altered with abnormal eye geometry, indicating a structural role for elastic fibers in optical tissues." (PMID 37001705, 2023). "Elastin-related hereditary diseases such as ectopia lentis, Marfan syndrome, pseudoxanthoma elasticum, and Sorsby fundus dystrophy can cause visual impairment and ocular pathology illustrating that elastic tissues are critical to function." (PMID 37001705, 2023). "Given its role in Marfan syndrome and its importance in elastin integrity, we assessed for levels of fibrillin-1 in the aorta." (PMID 36104385, 2022). "Compared to the increased cfPWV demonstrated in Marfan syndrome, these results converge toward a more localized alteration of the elastin fibers among large vessels." (PMID 31024329, 2019). "It has been reported that the elastin microfibrillar bundles are significantly reduced in a mouse model of Marfan’s syndrome, which is a type of collagen disease." (PMID 29802262, 2018). "In Marfan syndrome models, the tunica media of the aorta, which normally contains elastin sheets and collagen, is fragmented, disorganized, and lost." (PMID 25917920, 2015). "AEPS is also associated with a myriad of other unique genetic disorders that often target collagen and elastin formation such as Marfan syndrome, Ehlers-Danlos syndrome, osteogenesis imperfecta, pseudoxanthoma elasticum, and Rothmund-Thomson syndrome, to name a few." (PMID 39323702, 2024). "Mutations in the fibrillin-1 gene (FBN1) are the causative factor for Marfan syndrome (MFS), a disorder of connective tissue morphology of which one of the consequences is a fragmentation of elastin fibers, which may be a reason for MFS-related aortic aneurysm." (PMID 38334666, 2024).
Marfan syndrome (continued). "Subsequently, soluble aortic extracts from Marfan syndrome patients and mice models induce macrophage chemotaxis, which can be neutralized by pre-treatment with anti-elastin (VGVAPG) antibody, lactose (EBP antagonist), or EDPs implying involvement of the EBP and EDPs in inflammatory processes." (PMID 37001705, 2023). "Marfan syndrome (MFS) is the most common genetic form of thoracic aortic aneurysm disease, caused by pathogenic variants of the microfibrillar protein fibrillin-1, an ECM component acting as scaffold for elastin, as well as contributing to TGF-β signaling." (PMID 35224059, 2022). "Moreover, in mouse models of Marfan syndrome, circumferential aortic strain has been shown to correlate with elastin fragmentation and reduced elastic lamellae in aortic vessel walls." (PMID 32801116, 2020). "Fragmentation of elastin is an important component of aneurysmal progression in Marfan syndrome." (PMID 29187826, 2017). "Furthermore, sex influenced the occurrence of elastin breaks in Marfan syndrome, since males showed a greater (P < 0.05) number of breaks than females." (PMID 29187826, 2017). "Patients with Marfan syndrome (MFS) develop thoracic aortic aneurysms as the aorta presents excessive elastin breaks, fibrosis, and vascular smooth muscle cell (vSMC) death due to mutations in the FBN1 gene." (PMID 36577770, 2022). "Precedence for this hypothesis comes from Marfan syndrome patients, where disarrayed and fragmented arterial elastin fibrils are a cardinal feature, giving rise to reduced carotid compliance and distensibility and ultimately life-threatening aortic root dissection." (PMID 32183856, 2020). "In bovine Marfan syndrome however, cystic medial necrosis is absent and elastin concentrations are reported to be normal." (PMID 26581331, 2015). "Heritable thoracic aortic disease affecting the elastin–contractile unit, including PRKG1 mutations, may have extra-aortic features, such as hypermobility or cutis laxa, Marfan syndrome-like or Ehlers–Danlos-like features, without fulfilling the diagnostic criteria for these syndromes." (PMID 33807627, 2021).
abdominal aortic aneurysm (37 papers, 2011 to 2025). Enlargement and ballooning of the vessel that supplies arterial blood to the abdomen, pelvis and legs. "Older SFAs had straighter adventitial collagen similar to human abdominal aortic aneurysms and elastase treated porcine aortas, suggesting that collagen straightening may be associated with degradation and fragmentation of elastin and a shift of the load-carrying capacity to collagen." (PMID 33279711, 2021). "Inflammation and elastin degradation are key hallmarks in the pathogenesis of abdominal aortic aneurysms (AAAs)." (PMID 37239088, 2023). "PGG is an elastin-stabilizing polyphenolic compound that has been proven beneficial in abdominal aortic aneurysm (AAA) animal models." (PMID 37479718, 2023). "The pathogenesis of abdominal aortic aneurysm involves vascular inflammation and elastin degradation." (PMID 35203568, 2022). "In contrast, 01BSUR treatment reduced the impact of Ang-II on elastin levels, prevent the destruction of elastic fibers within the aortic wall and therefore the development of abdominal aortic aneurysms." (PMID 33216687, 2020). "Gelatinases, including MMP-2 and -9, can degrade elastin molecules and are upregulated in diseases of reduced elasticity, including abdominal aortic aneurysm and pulmonary fibrosis." (PMID 30067795, 2018). "Chronic inflammation and degradation of elastin are the main processes in the development of abdominal aortic aneurysm (AAA)." (PMID 26918963, 2016). "The aorta is rich in elastin and a cluster of abdominal aortic aneurysms has been reported." (PMID 35906498, 2023). "The suggested underlying mechanisms involve decreased matrix metalloprotease-2 activity and preservation of elastin and reduced calcification, thus, cycloastragenol could be considered for trial in abdominal aortic aneurysm patients." (PMID 35203568, 2022). "In addition, high expression of ITGAM is associated with unstable atherosclerotic plaques, and ITGAM knockout reduces macrophage infiltration, MMP9 expression, and elastin and collagen degradation in mouse abdominal aortic aneurysm models." (PMID 35656397, 2022). "Rationale: The progressive disruption of extracellular matrix (ECM) proteins, particularly early elastin fragmentation followed by abnormalities in collagen fibril organization, are key pathological processes that contribute to dissecting abdominal aortic aneurysm (AAA) pathogenesis." (PMID 34646388, 2021). "In addition, an inverse correlation of circulating miR-195 was observed in the presence of abdominal aortic aneurysms and increased aortic diameter, which is in line with the targets of miR-195, including collagens, proteoglycans and elastin." (PMID 32492915, 2020). "For example, MKEY was shown to suppresses abdominal aortic aneurysm formation and progression, reducing aortic diameter enlargement, preserving medial elastin fibres and smooth muscle cells, and attenuating mural macrophage infiltration, angiogenesis, and aortic metalloproteinase 2 and 9 expression." (PMID 30006564, 2018). "In AngII infused mice, abdominal aortic aneurysms appear to be initiated by rapid medial macrophage accumulation co-localized with focal elastin fragmentation, and these changes are followed by rapid luminal expansion and marked leukocyte infiltration in the adventitia." (PMID 24244746, 2013). "Macrophages are not only able to be attracted by elastin fragments, but can themselves produce the elastin precursor elastin, and may contribute to the increase in tropoelastin content that is characteristic of human abdominal aortic aneurysms and atheromas." (PMID 21647416, 2011). "A limitation of the present study is that murine and human abdominal aortic aneurysms occur in different anatomic sites (suprarenal versus infrarenal), which may reflect regional differences in collagen and elastin composition and thus give rise to different mechanical properties." (PMID 32094414, 2020).
abdominal aortic aneurysm (continued). "This conclusion aligns with previous studies, such as the inhibition of NLRP3 inflammasome, coincident with the downregulation of MMP2 expression in the lesion site of abdominal aortic aneurysm (AAA), and the prevention of elastin degradation." (PMID 38992615, 2024). "SAA has been also shown to play a role in the formation of abdominal aortic aneurysm in an experimental mouse model by triggering matrix metalloproteinase 2 (MMP-2) activity and ensuing elastin degradation." (PMID 34534311, 2021). "Timp3-deficiency suppressed the hypertensive response to Ang II, however induced abdominal aortic aneurysm (AAA) after 4 weeks of Ang II infusion, due to degradation of the elastin fibers and adverse remodeling of the aortic wall." (PMID 32612540, 2020). "MiR-181b is increased in human atherosclerotic plaques and abdominal aortic aneurysms (AAA), and inhibition of miR-181b suppressed the development and progression of atherosclerosis and aneurysms through increasing expression of TIMP3, elastin, and collagen." (PMID 32612540, 2020). "In addition, PGG can be used as a non-cytotoxic elastin stabilizer in the treatment of abdominal aortic aneurysm model rats." (PMID 33897423, 2021).